COMMD5 (COMM domain containing 5)
Description:
Scaffold protein in the commander complex that is essential for endosomal recycling of transmembrane cargos; the commander complex is composed of the CCC subcomplex and the retriever subcomplex. May modulate activity of cullin-RING E3 ubiquitin ligase (CRL) complexes. Negatively regulates cell proliferation (By similarity). Involved in kidney proximal tubule morphogenesis (By similarity). Down-regulates activation of NF-kappa-B.
Synonyms: HCaRG; HT002; FLJ13008
Tractability: PROTAC: its protein half-life has been measured.
Gene: Protein-coding gene on chromosome 8 (144,837,978 to 144,853,736, reverse strand). Ensembl gene ENSG00000170619.
Subcellular location: Cytoplasm; Nucleus
Subcellular location (Human Protein Atlas): Cytosol; Nucleoplasm
Pathways (Reactome):
Metabolism of proteins: Neddylation
Gene Ontology:
Molecular function: protein binding
Biological process: endocytic recycling
Cellular component: cytoplasm; cytosol; nucleoplasm; nucleus; protein-containing complex; endoplasmic reticulum membrane; endosome membrane
Genetic constraint (gnomAD): Loss-of-function variants: 14 observed, 12.06 expected, observed/expected ratio (o/e) 1.16, 90% interval 0.76 to 1.75. The upper end of that interval is the gene's LOEUF score, 1.75, which puts it in group 6 of 6, group 1 being the genes least tolerant of losing a copy. Missense variants: 234 observed, 292.65 expected, observed/expected ratio (o/e) 0.8, 90% interval 0.72 to 0.89. Synonymous variants: 127 observed, 128.76 expected, observed/expected ratio (o/e) 0.99, 90% interval 0.85 to 1.14.
Homologues: Orthologues: chimpanzee COMMD5 (99% identical), macaque COMMD5 (96% identical), guinea pig COMMD5 (88% identical), pig COMMD5 (87% identical), dog COMMD5 (85% identical), rabbit COMMD5 (82% identical), mouse Commd5 (79% identical), rat Commd5 (79% identical), tropical clawed frog commd5 (51% identical), zebrafish commd5 (44% identical), Drosophila melanogaster LSm-4 (19% identical).
Diseases named in the same sentence as COMMD5 in open-access papers:
COMMD5 is named in the same sentence as 24 diseases in open-access papers, as found by Europe PMC text mining. Sharing a sentence is not in itself a finding about the gene and the disease. The quoted sentences say what the papers report.
Hypertension (5 papers, 2014 to 2023). The presence of chronic increased pressure in the systemic arterial system. "COMMD5, also known as hypertension-related, calcium-regulated gene (HCaRG), is strongly expressed in renal proximal tubules, where it regulates cell proliferation and differentiation, and accelerate the repair of renal tubules." (PMID 36776284, 2023). "COMMD5, which is also known as HCaRG, is a hypertension-related calcium regulatory gene that inhibits the expansion of tumor cells." (PMID 36092163, 2022). "COMMD5 was previously known as the hypertension-related, calcium-regulated Gene (HCaRG) as its first known function was to regulate the growth of renal epithelia." (PMID 34943955, 2021). "Our review focuses here on a hypertension-related gene, hypertension-related, calcium-regulated gene (HCaRG/COMMD5) that is more expressed in kidneys of SHR than of normotensive rats, and could explain in part the resistance of the SHR kidney by its accelerating effects on renal repair." (PMID 24515317, 2014).
gastric cancer (4 papers, 2014 to 2024). A primary or metastatic malignant neoplasm involving the stomach. "In gastric cancer, the most significant mutation information was associated with COMMD5." (PMID 38817875, 2024). "COMMD5 also inhibits proliferation of renal carcinoma cell and gastric cancer cell 16-18." (PMID 35399735, 2022). "However, the precise function of COMMD5 in gastric cancer requires additional investigation." (PMID 36776284, 2023).
renal carcinoma (4 papers, 2017 to 2022). A carcinoma arising from the epithelium of the renal parenchyma or the renal pelvis. "COMMD5/HCaRG overexpression inhibited tumor growth and angiogenesis in a homograft renal carcinoma mouse model by promoting de-phosphorylation of ErbB2/HER2, ErbB3/HER3, and EGFR, leading to inhibition of ErbB signaling pathways." (PMID 33768002, 2021). "Their research also indicated that lower COMMD5 expression was found in renal carcinoma and COMMD5 suppress cancer development via cell growth, migration, and differentiation." (PMID 34493238, 2021). "We also found that several shallow deletions and some deep deletions correlated with COMMD5 mRNA downregulation and this is more pronounced in breast invasive carcinoma, colorectal, lung and renal cancer including ccRCC and chromophobe RCC." (PMID 33768002, 2021).
melanoma (2 papers, 2017 to 2021). A malignant, usually aggressive tumor composed of atypical, neoplastic melanocytes. "COMMD1, COMMD5, and COMMD10 are known to act as tumor suppressors, and their expression levels are reduced in several cancers including cancers, seminoma, melanoma, as well as kidney, pancreatic, colorectal, and ovarian cancers." (PMID 34943955, 2021). "COMMD5 as a tumor suppressor regulates several tumorigenic kinases: it inhibits epidermal growth factor receptor (EGFR) expression and phosphorylation in kidney cancers and suppresses the MAPK and PI3K/AKT signaling pathways in renal carcinoma and melanoma cells." (PMID 34943955, 2021).
acute kidney injury (1 paper, 2014). Sudden and sustained deterioration of the kidney function characterized by decreased glomerular filtration rate, increased serum creatinine or oliguria. "Recently, we reported that transgenic (Tg) mice overexpressing HCaRG/COMMD5 in RPTs recovered rapidly from the inflammatory burst that increased TNF-α and IL-1β as well as infiltration of macrophages after acute kidney injury (AKI)." (PMID 24515317, 2014).
breast invasive carcinoma (1 paper, 2021). "Furthermore, downregulation of COMMD5 expression correlated with 8q loss in invasive breast cancer, colorectal and lung cancers and in ccRCC and chromophobe RCC." (PMID 33768002, 2021). "Interestingly, gain of chromosome 8q were noted in cancers with higher levels of COMMD5 mRNA, including breast invasive carcinoma, oesophagus, liver, and uterine cancers." (PMID 33768002, 2021).
Cirrhosis (1 paper, 2012). A chronic disorder of the liver in which liver tissue becomes scarred and is partially replaced by regenerative nodules and fibrotic tissue resulting in loss of liver function. "The cytoskeleton (COMMD5, KRTAP19-5, LLGL1 and SNX17) related genes were down-regulated in cirrhosis (F4)." (PMID 22397681, 2012).
leukemia (1 paper, 2021). A malignant (clonal) hematologic disorder, involving hematopoietic stem cells and characterized by the presence of primitive or atypical myeloid or lymphoid cells in the bone marrow and the blood. "Among cancer associated to COMMD5 mutations were prostate, breast, lung carcinoma, leukemia, and RCC." (PMID 33768002, 2021). "They identified recurrent DNA amplifications, and gain of chromosomic region mapping the locus of COMMD1, COMMD5, and COMMD3 have been reported in lymphoma, leukemia, colorectal cancer, hepatocellular carcinoma, and oral squamous cell carcinoma." (PMID 33768002, 2021).
lung carcinoma (1 paper, 2021). "A down-regulation of COMMD5 has been observed in renal and lung cancer and in human gastric cancerous tissue." (PMID 33768002, 2021).
ovarian carcinoma (1 paper, 2021). A malignant neoplasm originating from the surface ovarian epithelium. "We found that copy-number gain of COMMD5 strongly correlated with its mRNA upregulation in prostate and ovarian cancers." (PMID 33768002, 2021). "High-level amplification of COMMD5 was observed in prostate and ovarian cancers." (PMID 33768002, 2021).
tumor (8 papers, 2017 to 2023). "However, we noted that COMMD5 is also the most frequently altered gene among the COMMD member that was associated to tumor progression." (PMID 33768002, 2021). "COMMD5, also known as hypertension-related calcium-regulated gene (HCaRG), has been shown to inhibit proliferation of tumor cell 16-18." (PMID 35399735, 2022). "COMMD5 is a tumor suppressor as it promotes cell proliferation and kidney regeneration in mice after trauma." (PMID 34943955, 2021). "HCaRG/COMMD5 acts as a tumor suppressor gene of RCC and as such restoring its levels to control EGFR/ErbB signaling holds potential to treat cancer." (PMID 29050225, 2017). "Among this family, COMMD5 emerged as a versatile modulator of tumor progression." (PMID 33768002, 2021). "We have shown that higher COMMD5 protein levels in normal tissue surrounding RCC tumors favored their differentiated phenotype, reduced tumor growth and enlargement, and correlated with survival rate and better prognosis of patients with RCC." (PMID 33768002, 2021). "Some abnormally regulated genes in our prognostic signature participated in tumour initiation and development, including NUMB, RSRC2, TMC6, CASP8, TRIO, and COMMD5." (PMID 34772375, 2021). "In renal cancer cells, COMMD5 decreases proliferation, improves differentiation, accelerates autophagic cell death, and lowers VEGF production through downregulating HIF-1α, ultimately inhibiting tumor angiogenesis." (PMID 36776284, 2023).
cancer (7 papers, 2017 to 2025). A tumor composed of atypical neoplastic, often pleomorphic cells that invade other tissues. "Among the 44 reported mutations associated to cancer, 34 were located on sequences specific to COMMD5, and only 10 were within the COMM domain, a highly conserved 70–85 residue C-terminal domain shared by all COMMD members." (PMID 33768002, 2021). "The data presented here demonstrate the duality of COMMD5 expression from down to upregulation, but both correlating with cancer susceptibility." (PMID 33768002, 2021). "Through its position on chromosome 8q24.3, COMMD5 is clearly a target for copy-number alterations, and thus a candidate gene for cancer susceptibility." (PMID 33768002, 2021). "Few genetic studies have related copy number variants (CNV) and COMMD5 transcripts to cancer progression." (PMID 33768002, 2021). "We previously showed that COMMD5 is associated to differentiated cell phenotype and is downregulated in different cancer cell lines and RCC." (PMID 33768002, 2021). "Screening for COMMD5 expression levels and somatic mutations in cancer should be initiated." (PMID 33768002, 2021). "So, small differences in COMMD5 expression could induce variations in cancer susceptibility, and its functional properties are strongly related to its level of expression." (PMID 33768002, 2021). "The novel observation that COMMD5 expression could be differently regulated in cancer cells by its locus alterations, amplifications, mutations or by telomere length, raises several questions with regards to its function and association to cancer." (PMID 33768002, 2021). "To determine the impact of COMMD5 amplification on its expression, we selected cancer studies with mRNA expression profiles." (PMID 33768002, 2021). "Amplification of TRIO and COMMD5 proteins has also been reported in various types of cancer, suggesting an oncogenic function." (PMID 34772375, 2021). "Here, we review some data concerning expression and role of COMMD5 and propose a novel rationale for the potential link between the subtelomeric position of COMMD5 on chromosome 8 and its contrasting functions in cancer." (PMID 33768002, 2021). "COMMD5 alterations have been detected in eight cancer studies, compared to four for COMMD2 and only one for COMMD9." (PMID 33768002, 2021). "Interestingly, we also found that COMMD5 chromosomic alteration leading to COMDD5 amplification and overexpression was also associated to cancer progression." (PMID 33768002, 2021). "Considering these observations, we propose that the variability of telomere length in different type of cancers could explain the variable expression of COMMD5 in cancers." (PMID 33768002, 2021). "In order to explain the variable levels of expression of COMMD5 in cancer, we assessed whether its localization at the end of chromosome 8 could regulate its level of expression in different cancers and during ageing process." (PMID 33768002, 2021). "COMMD5/HCaRG is the second COMMD protein most published in relation to cancer." (PMID 33768002, 2021). "Is COMMD5 a promising therapeutic target for cancer therapy?" (PMID 33768002, 2021). "Here, we focused on the localization of COMMD5 at the subtelomeric position of the chromosome and developed a rationale that this could impact on COMMD5 gene regulation in cancer cells." (PMID 33768002, 2021). "We suggest that TPE-OLD could be one of the mechanisms responsible for differential transcriptional levels of COMMD5 in cancer." (PMID 33768002, 2021). "Surprisingly, these studies observed an amplification of COMMD5 that may paradoxically promote cancer progression." (PMID 33768002, 2021). "Accordingly, two opposing functions could be proposed for COMMD5 in cancer." (PMID 33768002, 2021). "Molecular mechanisms that modulate COMMD5 expression in cancer have not yet been elucidated, offering a wide range of possibilities." (PMID 33768002, 2021).
cancer (continued). "Indeed, using cbioportal database, we analyzed COMMD5 mRNA expression relative to normal samples (non-cancerous samples) in several cancer types using the data generated by the Cancer Genome Atlas (TCGA)." (PMID 33768002, 2021).
COMMD5 also shares sentences with these, for which no sentence is quoted: renal cell carcinoma (3 papers); atherosclerosis (1); autoimmune disease (1); fibrolamellar hepatocellular carcinoma (1); hepatocellular carcinoma (1); kidney diseases (1); liver fibrosis (1); metabolic syndrome (1); non-small cell lung carcinoma (1); pancreatic ductal adenocarcinoma (1); renal adenocarcinoma (1); systemic lupus erythematosus (1).